CXCL10 (C-X-C motif chemokine ligand 10)
Diseases named in the same sentence as CXCL10 in open-access papers (continued):
Sharing a sentence is not in itself a finding about the gene and the disease.
viral infection (continued). "Thus, due to the effect of virally induced Th1 cytokines, CXCL10 might predominate over CCL20 during BKPyV replication, indicating that different virus infections might indeed elicit different patterns of chemokine responses." (PMID 31981424, 2020). "As part of the innate immune response against virus infections targeting the respiratory tract, such as influenza virus or RSV infection, JEV infection of porcine NEC also induced several chemokines (CCL2, CCL5, and CXCL10), which would direct the migration of monocytes to the site of infection." (PMID 30282716, 2018). "CXCL10 protein levels had negative associations with FEV1, independent of viral infection." (PMID 30463560, 2018). "Similarly, the CSF of the fetus had significantly elevated levels of IL-1RA, Eotaxin (CCL-11), MCP-1 (CCL-2) and IP-10 (CXCL-10) compared to the maternal CSF (p < 0.05, one-way ANOVA), which could be indicative of an ongoing viral infection." (PMID 29343712, 2018). "Indeed, CXCL10 was reported to be a key regulator of the cytokine storm in SARS-CoV-2 infection, CXCL1 to play a role in chemotactic neutrophils in bacterial infections, and OASL to be involved in IFN-gamma signaling and PI3K-Akt signaling pathways, which can restrict virus infection." (PMID 34899651, 2021). "However, N2 reduced the expression of chemokine CXCL10, which is regulated by an IRF3-responsive promoter, from cells infected with Newcastle disease virus (NDV), providing further evidence of its ability to inhibit the IRF3-dependent innate immune response to virus infection." (PMID 23761407, 2013). "Moreover, proinflammatory cytokines, such as IL-1, IL-8, CXCL10, IL-6, and TNF-α, are known to be released within hours after inflammation challenge and serve as unspecific alarm signals, as they are released during viral infection, asthma and atopic dermatitis." (PMID 21909400, 2011). "Additionally, PDCoV infection increased the transcription of the chemokines CCL2, CCL4, CXCL9, CXCL10 and CXCL11, suggesting that these chemokines may contribute to the recruitment and regulation of macrophages or other inflammatory cells to the sites of virus infection." (PMID 35328701, 2022). "CXCL10 is secreted by monocytes, endothelium, and fibroblasts after IFN-γ (interferon gamma) stimulation in response to viral infection, and after LPS stimulation in response to Gram-negative infection." (PMID 29661181, 2018). "However, we detected no further induction of IFN-α after virus infection despite a surge of pro-inflammatory responses (IL-6, IL-1β, TNF-α, IFN-γ CCL2, CCL3, and CXCL10) compared to mature hamsters." (PMID 37122119, 2023). "By incubating Calu-1 cells with IMD-0354 (without subsequent viral infection), we also observed increased expression of IFN-β, CXCL10, and IL-6 with 15, 9, and 36-folds, respectively; and the activation of these genes was counteracted by BX795, a TBK1/IKKε inhibitor that blocks IFN-β production." (PMID 36093376, 2022). "In particular, fatal disease was characterized by upregulated levels of IP9/CXCL11 and IP10/CXCL10, which are also expressed by microvascular endothelial cells upon activation or infection with dengue virus, suggesting a general rather than SARS-CoV-2-specific response to viral infection." (PMID 35141292, 2021).
melanoma (277 papers, 2007 to 2026). A malignant, usually aggressive tumor composed of atypical, neoplastic melanocytes. "In particular, both CCL5/Rantes and CXCL10/IP10 mRNA, and their corresponding secreted proteins, were significantly up-regulated in autophagy-deficient melanoma cells." (PMID 40611330, 2025). "Patients with advanced melanoma, which is associated with a poor prognosis, have higher levels of CXCL10." (PMID 39780275, 2025). "A higher expression of CCL2, CCL3, CCL4, CXCL9 and CXCL10 transcripts was associated with more CD8+ T cell recruitment into melanoma metastases." (PMID 38928238, 2024). "Upregulation of CXC motif chemokine 10 (CXCL10) in melanoma patients has been found to be associated with melanoma progression." (PMID 39268223, 2024). "Melanoma differentially expressed genes positively associated with high APRIL/CXCL10/CXCL13 tumor expression were linked to tumor infiltration by a diverse array of proinflammatory immune cell types." (PMID 37435077, 2023). "Only serum CXCL10 levels exhibited significant differences across patients harboring melanomas with different mutations (BRAF, CDKN2A, NF, NRAS)." (PMID 37435077, 2023). "CXCL10 was upregulated in metastasis-associated astrocytes in mice and humans and was functionally important for the chemoattraction of melanoma cells." (PMID 36527157, 2022). "In murine models of adenocarcinoma, glioma and melanoma, intratumoural CXCL10 injection is associated with impaired growth and metastasis." (PMID 35844527, 2022). "It has been shown in vivo that CXCR3-deficient NK cells cannot migrate to CXCL10-positive B16 melanoma tumor cells." (PMID 34768814, 2021). "In humans, the chemokines CCL2, CCL3, CCL4, CCL5, CXCL9, and CXCL10 have been associated with increased T cell infiltrates in melanomas, and the same chemokines were confirmed to attract human CD8+ T cells in vitro." (PMID 34454518, 2021). "More specifically, the production of CXCL9 and CXCL10, among other proinflammatory cytokines, has been associated with the severity of melanoma and metastasis." (PMID 34568099, 2021). "RT-qPCR assays demonstrated that Ccl2/Ccr2 and Cxcl9/Cxcl10/Cxcr3 levels were higher in B16 melanoma tumors from Cbx3/HP1γ-deficient mice than those from controls." (PMID 34721405, 2021). "For instance, CXCL10 (IP-10) exerts both pro-and anti-melanoma effects, mostly due to splice variants of its CXCR3 receptors." (PMID 33302400, 2020). "Earlier reports showed lymphocyte-independent activity of CXCL10 in xenografts of human melanoma in immune-deficient hosts." (PMID 29163806, 2017). "Expression of CXCR3 on circulating T cells or its chemokine ligands, CXCL9 and CXCL10, in tumor tissues has been reported to be associated with elevated intratumoral T cell infiltration in melanoma and colorectal cancer patients." (PMID 28407741, 2017). "The expression of chemokines such as CCL5, CXCL10 and others were associated with malignant melanoma progression." (PMID 26197340, 2015). "CXCL10 levels augmented in advanced melanoma patients are associated with poor clinical outcomes." (PMID 39268223, 2024). "On the other hand, it has been shown that LPS activation of murine melanoma-associated MCs induces CXCL10 secretion and promotes T cell recruitment, which, in turn, could enhance immunosurveillance against melanoma tumors." (PMID 35883682, 2022). "CXCL9 and CXCL10 expression was associated with CD8+ T cell-infiltrated melanoma metastases." (PMID 34503058, 2021). "Importantly, CXCL10 levels are elevated in advanced melanoma patients, and were associated with poor clinical outcomes." (PMID 33466236, 2021). "For example, CXCL10 expression was associated with T lymphocyte recruitment in melanoma metastases." (PMID 32582551, 2020). "Thus, it has been shown that the expression of CCL4, CCL5, and CXCL10 in melanoma metastases is associated with the recruitment of CD8+ T cells." (PMID 30984181, 2019).
melanoma (continued). "Furthermore, CXCL9 and CXCL10 expression in primary melanoma samples from patients was associated with greater CD8+ T cell infiltration whereas biopsies taken from metastatic lesions were lower." (PMID 30899263, 2019). "In addition to T cells, CXCL10 can also promote the trafficking of adoptively transferred NK cells into melanoma where they cause regression of the tumor mass." (PMID 30320116, 2018). "Interestingly, the increase of CXCL10 has also been associated with advanced human cancers such as malignant melanoma." (PMID 30266743, 2018). "Moreover, macrophages are a major source of CCL2, CCL3, CCL4, CCL5, CXCL9 and CXCL10, which are important chemokines that induce T lymphocyte chemotaxis, and which we find in association with stromal activation in actual melanomas." (PMID 28448494, 2017). "Likewise, CXCL10 has been shown to repulse plasmacytoid dendritic cells; interestingly CXCL10 has also been shown to inhibit angiogenesis and overexpression or mutation of CXCL10 in melanoma cells results in slower growth of xenografts." (PMID 24810760, 2014). "Namely, mice with melanoma tumors demonstrated higher levels of CXCL10, IL-6, and CCL2 in the serum compared to mice with control breast carcinoma tumors." (PMID 39857957, 2025). "CXCL10 is a well-known chemokine; validating its chemotactic effect on immune cells towards melanoma cells or within the TME using Transwell migration assays would be essential." (PMID 40607411, 2025). "Astrocyte-secreted CXCL10 has been demonstrated to facilitate the migration of melanoma cells toward astrocytes." (PMID 40076927, 2025). "ZEB1 impairs the recruitment of immune cells into the TME by downregulating CXCL10 production, which is necessary for T cells to enter the tumor and attack melanoma cells." (PMID 40872475, 2025). "For instance, in melanoma, the chemokine CXCL10 increases NK cell infiltration in the TME and reduces tumor growth in vitro." (PMID 40211394, 2025). "This axis is primarily driven by IFN-γ, and its activation via intra-tumoural IFN-γ delivery increases CXCL10/11 levels in melanoma." (PMID 40361472, 2025). "The three-gene KRAS-Macrophage Prognostic Associated Gene (KMPAG) signature, encompassing CLEC4A, CXCL10, and LAT2, emerges as a robust prognostic tool that correlates with distinct clinical and immunological phenotypes in melanoma cohorts." (PMID 40607411, 2025). "PD-1 blockade increases tumoural CXCL10 in ACT-treated melanoma, while ipilimumab elevates CXCL9–11 levels." (PMID 40361472, 2025). "Together this data confirms that constitutive IκBζ expression in melanoma contributes to immunotherapy resistance, supposably by suppressing Ccl5, Cxcl9, and Cxcl10 expression, leading to a continuous exclusion of cytotoxic T cells and NK cells from the TME." (PMID 40562773, 2025). "For example, elevated CXCL10 levels in melanoma biopsies have been shown to predict a strong clinical response to anti–PD-1 therapy." (PMID 41516196, 2025). "In this study, we show that coadministration of GUA and MAPKi increased melanoma CXCL9/CXCL10 secretion." (PMID 39867570, 2025). "For example, in melanoma, renal cell carcinoma, and other tumors with strong interferon signaling, CXCL10 enhances STAT1-driven T-cell activation." (PMID 40760734, 2025). "In M160915, GUA induced strong upregulation of the T-cell chemokines CXCL9 and CXCL10, which were previously reported to be expressed in highly T-cell–infiltrated melanoma." (PMID 39867570, 2025). "Elevated levels of CXCL10 following anti-PD1 treatment was observed in melanoma patients who responded to immune checkpoint blockade." (PMID 40589738, 2025). "In conclusion, IκBζ expression in melanoma inhibits tumor infiltration of cytotoxic T cells, probably by suppressing the expression of chemokines, such as Ccl5, Cxcl9, and Cxcl10." (PMID 40562773, 2025).
melanoma (continued). "The data presented in this manuscript focus on CCL5 and CXCL10 as key indicators for evaluating the impact of regulating the expression of ACKR2 in melanoma model." (PMID 40248897, 2025). "In a clinical trial of melanoma, increased expression of chemokines CXCL9 and CXCL10 after neoadjuvant immunotherapy was highly associated with antitumor efficacy." (PMID 39164491, 2024). "This melanoma tumor-induced host-expressing CXCL10 played critical roles in melanoma angiogenesis and tumor growth by acting on melanoma cancer cells to induce activation of pro-growth and pro-angiogenic signals and expression of pro-angiogenic factors." (PMID 39268223, 2024). "ERK, AKT, and CREB signals, which are activated by CXCL10, also play important roles in melanoma proliferation and growth." (PMID 39268223, 2024). "In preclinical experiments, the major source of CXCL10 within melanomas appeared to be, again, Batf3-lineage DCs, suggesting the key role of these DCs in the anti-tumor T cell response." (PMID 38928238, 2024). "Results presented in the current report support the role of amplified CXCL10 in conferring a pro-tumorigenic function in melanoma development, thereby suggesting a potential strategy to target CXCL10 for melanoma therapy." (PMID 39268223, 2024). "After treatment with polymeric cGAMP-loaded NPs, CXCL-10 expression in melanoma TDLN was upregulated, consistent with a significant increase in CD8+ T cell infiltration in TME." (PMID 38185685, 2024). "CXCL10 induced expression of pro-angiogenic factors in B16F10 melanoma cells and subsequent tube formation of human umbilical vein endothelial cells (HUVECs) in vitro." (PMID 39268223, 2024). "Further investigation into the modulation of the cytokine CXCL10 in melanoma cell lines corroborated our findings." (PMID 39061208, 2024). "Consistent with this, paracrine Cxcl9 and Cxcl10 was significantly upregulated after the introduction of K510A mutant EZH2 into melanoma cells with endogenous EZH2 silencing." (PMID 38461299, 2024). "Human melanoma cells have been demonstrated to be capable of producing CXCL10, which can be induced by some tumor microenvironmental stimuli, such as IFNγ and toll-like receptor (TLR) agonists." (PMID 39268223, 2024). "CXCR3 ligands such as CXCL9 and CXCL10 as indirect markers of T-cell infiltration have been identified in the past as indicating a response to ICI in stage IV melanoma." (PMID 38562921, 2024). "In this study, using B16F10 murine melanoma tumor cells with Cxcl10-/- syngeneic C57BL/6 mice, we demonstrated that host-derived endogenous CXCL10 was amplified during subcutaneous B16F10 melanoma tumor growth." (PMID 39268223, 2024). "In particular, overexpression of CXCL10 and CXCR3 has been associated with advanced human cancers, including malignant melanoma." (PMID 39268223, 2024). "CXCL10, upregulated in melanoma tissues, recruits CD8+ T cells and NK cells to tumors, promoting anti-tumor immune responses, and serving as a predictive marker for immunotherapy outcomes." (PMID 39355255, 2024). "Together, our findings reveal that amplified host-derived endogenous CXCL10 is critical for B16F10 melanoma angiogenesis and tumor growth." (PMID 39268223, 2024). "In a study using irradiated EBV-LCL feeder cells with IL-2, the increased expression of CXCR3 by NK cells led to improved homing and tumor-killing activity against CXCL10-transfected melanoma xenograft mice." (PMID 39339180, 2024). "Upregulation of Cxcl9 and Cxcl10 was detected after Mi-2β silencing and anti-PD-1 treatment in melanomas." (PMID 38461299, 2024). "Our data revealed heightened expression of CD8+ T cell markers (CD8a and CD8b) and NK cell markers (NCR1 and NCR3) in melanoma patients with elevated levels of cGAS/CCL5/CXCL10." (PMID 38506049, 2024). "A significant relationship between the infiltration of CD8+ T cells and the expression of CCL5 and CXCL10 has been shown in Ewing sarcoma, melanoma, esophageal cancer, and colorectal cancer." (PMID 39108499, 2024).
melanoma (continued). "We and others have previously reported that CXCL10/CXCR3 signaling plays critical roles in melanoma tumor cell motility and metastases to the bone, lung, and brain, accompanied with elevated CXCL10 levels in a mouse model of spontaneous melanoma metastasis." (PMID 39268223, 2024). "Similar results were shown in an in vivo and in vitro melanoma model with an adenovirus vector expressing CXCL10." (PMID 38928238, 2024). "Taken together, these results indicate that CXCL10 can induce expression of pro-angiogenic factors in B16F10 melanoma cells, which can enhance angiogenesis in vitro." (PMID 39268223, 2024). "In the present study, the amplified CXCL10 mainly from host-cells through interaction with melanoma cells was shown to be critical in melanoma angiogenesis and tumor growth via paracrine CXCL10 signaling." (PMID 39268223, 2024). "In melanoma and CRC tumor models, the effects are NK and CD8+ T cell‐dependent and associated with increased levels of chemokines CCL5 and CXCL10." (PMID 38506049, 2024). "Several signaling pathways involved in production of pro-angiogenic factors and tumor growth were activated by CXCL10 in B16F10 melanoma cells." (PMID 39268223, 2024). "Astrocytes were shown to be activated by melanoma-secreted factors and upregulated the CXCL10 expression, which subsequently drove melanoma cells migration toward astrocytes." (PMID 37190188, 2023). "In melanoma patients, CXCL10 expressed by immune cells in the tumor has been identified as a predictive factor for response to immunotherapy." (PMID 37501121, 2023). "Synergistic effects against established subcutaneous melanoma tumours were previously observed with treatment involving intra‐tumoural injection of CXCL10 or CXCL9 combined with IL‐12 treatment and was reported to cure 80% of mice." (PMID 37170733, 2023). "DPP4 has been shown to regulate C-X-C motif chemokine ligand 10 (CXCL10)-mediated lymphocyte migration in mouse melanoma- and hepatocellular carcinoma-transplanted tumors." (PMID 37115489, 2023). "Upon upregulation of CXCL10, an inflammatory chemokine derived from astrocytes related to metastases, encephalophilic melanoma cells can correspondingly elevate the receptor CXCR3." (PMID 38104104, 2023). "Together these data suggest that 3-component index that integrates high expression of APRIL/TNFSF13, CXCL10, and CXCL13 transcripts in tumor are associated with superior melanoma patients' survival and a pro-inflammatory TME supportive of LA and /or TLS." (PMID 37435077, 2023). "In a mouse study, CD8+ T cell infiltration in HCC was induced by CXCL10 expression, and patients with melanoma who responded to therapy had higher plasma CXCL9 and CXCL10 levels after ICI therapy." (PMID 38133557, 2023). "To further assess candidate NR2F6 effectors, we first validated NACC1, FKBP10, and CXCL10 expression levels in NR2F6 KD or KO mouse melanoma cells." (PMID 37406115, 2023). "CXCL10 has been shown to be a crucial chemokine for drawing CD8+ T lymphocytes into melanoma tumors in preclinical models." (PMID 37875556, 2023). "Evidence suggests that CXCL10 is necessary for recruitment of antitumoral T cells into melanoma tumors." (PMID 36445410, 2023). "Another aspect of the activation of STING signaling in melanoma cells is the downstream induction of CXCL10 and CCL529." (PMID 36949064, 2023). "We observed that melanoma patients with coordinately high serum levels of APRIL and coordinate high APRIL/CXCL10/CXCL13 we're associated with improved survival and proinflammatory TME." (PMID 37435077, 2023). "Both DTIC and TMZ have been found to cause melanoma cells to secrete chemokines like CCL5, CXCL9, CXCL10, and CXCL11 in an animal model of melanoma." (PMID 38057843, 2023). "In fact, intratumoral CXCL10 is shown to be a positive prognostic factor for response to immunotherapy in other cancers such as melanoma." (PMID 37175780, 2023).